TNF (tumor necrosis factor)
Diseases named in the same sentence as TNF in open-access papers (continued):
Sharing a sentence is not in itself a finding about the gene and the disease.
infection (continued). "Under pathological conditions such as stress, infection, or neurodegenerative diseases, pro-inflammatory cytokines, including tumor necrosis factor alpha (TNF-α), interleukin-1 beta (IL-1β), and interleukin-6 (IL-6), are released in excess." (PMID 39517142, 2024). "MEndoB showed a dose-dependent effect on cytokine TNF-α concentration measured at 48 h post-infection, with concentrations in the 10 mg/kg and 1 mg/kg groups significantly lower than those in the 0.1 mg/kg group." (PMID 38275913, 2024). "Infection with CHIKV also increased the levels of inflammatory cytokines and chemokines (TNF-α, IL-6, IL-10, and CCL-2), which are associated with severity, morbidity, and mortality in patients." (PMID 39339151, 2024). "These cells were functionally potent, produced high levels of IFNγ and TNF and efficiently protected animals from secondary infection." (PMID 39107476, 2024). "Throughout the infection, we noted that pro-inflammatory factors such as IL-1β and TNF-α consistently increased in both serum and liver tissue, while anti-inflammatory factors like IL-4 and IL-10 showed a continuous decline." (PMID 39749332, 2024). "There is an increased recruitment of MHCII-Ly6C+ monocytes to the infection site and an increase in inflammatory mediators such as TNF-α, IL-12, IL-23, IL-1b and IL-6, as well as activation of other inflammatory cells, including Th1 or Th17 cells." (PMID 39081865, 2024). "Infection with SARS-CoV2 affects the immune system and causes an increase in interleukin (IL)-6, IL-8, tumor necrosis factor-α (TNF-α), and other cytokines." (PMID 38594493, 2024). "MIR155HG and TNF-a were positively correlated with the incidence of infection, renal damage and cardiac damage (r=0.623, 0.533 and 0.621; r=0.431, 0.498 and 0.552) (P<0.05)." (PMID 38699702, 2024). "The mammalian antiviral immune responses induced by type I IFNs and proinflammatory cytokines, including IL-1β and TNF-α, represent the first line of host defense upon infection." (PMID 38501350, 2024). "In line with this idea, our findings indicate that in healthy close contacts and LTB, ADAM17 acts principally by shedding TNF to maintain concentrations sufficient to keep infection control below a pathological threshold." (PMID 38881671, 2024). "Expression of specific protein markers such as TMPRSS2, ACE2, Alix, TSG101, CDs, TLRs, TNF-α, and others were altered in infection-derived EVs when compared to control-derived EVs after FCoV infection." (PMID 39091390, 2024). "Highly-expressed MIR155HG and TNF-α would promote the occurrence of such complications as infection, renal damage and cardiac damage in SLE patients." (PMID 38699702, 2024). "Reactivation of controlled infection after TNF inhibitors or immune suppression post solid organ transplant has been reported." (PMID 38667927, 2024). "Perhaps the importance of TNF in response to E. africanus occurs earlier and would have been missed in our kinetic studies starting at one-week post-infection." (PMID 38198478, 2024). "We used Ms-pVV2 and Ms-PE_PGRS38 for infection of RAW264.7 macrophages to study their effects on TNF-α, IL-1β, IL-6, and IL-10 mRNA expression." (PMID 38785795, 2024). "Our previous data show that IFNγ fuels the infection of mouse and human astrocytes by T. cruzi via autocrine TNF production." (PMID 38776344, 2024). "RM display an anti-inflammatory profile in peripheral monocytes even before infection, with reduced IFN-γ secretion, whereas CM show a stronger pro-inflammatory response, particularly the release of TNF-α, during early infection." (PMID 39949719, 2024). "The proportion of multi-functional T cells decreased while monofunctional T cells (CD107a+/IFN-γ-/TNF-α-/IL-2-) gradually increased from day 60 after Cl-13 infection." (PMID 38547316, 2024). "Specifically, ILC1s produce IFN‐γ and TNF, effectively curbing bacterial replication and aiding infection control." (PMID 38898983, 2024).
infection (continued). "Crucially, Fx completely abrogated the TNF-increased Ser/5-HT-promoted infection of U-87 MG cells by T. cruzi." (PMID 38776344, 2024). "M1 macrophages can control infection by releasing a wide spectrum of factors including IL-1β, TNF-α, IL-6, and iNOS expression." (PMID 37227688, 2024). "In contrast, infection with the Omicron, yielded a slight increase in TNF-α secretion with less amount of IL-1β and Interleukin 2 (IL-2) compared to wild-type." (PMID 38568894, 2024). "shows that the IL-6 and TNF-α levels increase during infection or tissue injury, and their low expression levels are of great significance to DF wound healing." (PMID 38464966, 2024). "Next, we found that the expression of proinflammatory mediators (IL‐6, IL‐8, IP‐10, MCP‐1, MIP‐1α, and TNF‐α) was substantially increased in cells that had been stimulated with IFN‐β before the infection with the H1N1 virus." (PMID 38617435, 2024). "While essential for containing the infection, excessive TNF production can lead to tissue damage and pathology associated with TB." (PMID 38892443, 2024). "In summary, we detected limited SARS-CoV-2–specific responses in early infection with a functional bias toward TNF-α." (PMID 38408318, 2024). "Upon infection, pro-inflammatory mediators such as TNFα or granulocyte-colony stimulating factor (G-CSF) are released by various cells at the inflammatory site, primarily by tissue macrophages." (PMID 38613695, 2024). "IL-10 (low dose: 17.65 pg/ml; high dose: 21.35 pg/ml) and TNF (low dose: 253.44 pg/ml; high dose: 296.59 pg/ml), showed comparable concentrations in the serum of mice infected with the low and high infection dose." (PMID 38979428, 2024). "The fact that TNF-α elicits a rapid response at a critical time, such as the 10th day after infection, and that IL-1β follows in the subsequent days serves as a crucial determinant in neuroimmunopathogenesis." (PMID 39766497, 2024). "Meanwhile, infection with the ΔbepA-G strain induced significant TNF-α secretion in RAW264.7 cells, while translocation of wild-type BepD impaired TNF-α secretion." (PMID 39531410, 2024). "Throughout the 21-day infection period, the levels of cytokines, such as IL-2, TNF-α, and IFN-γ were much lower in PD-1+TIM-3+ exhaustion-like CD8+ T cells than in PD-1+TIM-3-CD8+ T cells, which are recognized as activated cells." (PMID 39664572, 2024). "The TNF-α and IL-1β cytokines in teleost fish are powerful pro-inflammatory cytokines released by several immune cells during infection or tissue damage." (PMID 39243089, 2024). "Next, we examined the production of IFN-γ and TNFα by TCD8+ in the VACV-infected ears of both mouse strains 5d or 8d post-infection." (PMID 38543790, 2024). "During pathogenic infection in the gut, innate and adaptive immune cells act together through IFN-γ and TNF-α secretion to enhance TLR4 mRNA and its protein expression by epithelial cells to induce pathogen recognition and innate immunity activation." (PMID 38473881, 2024). "Representative pro-inflammatory cytokines, including IL-1β, IL-6, and TNF-α, are secreted upon infection and tissue damage, promoting the migration of immune cells to the inflammatory site and amplifying the inflammatory response." (PMID 39727927, 2024). "First, widespread inflammation is triggered in response to infection, and the proinflammatory cytokines, chemokines, and mediators such as tumor necrosis factor-α (TNF-α), interleukin-1β (IL-1β), IL-6, IL-8, and proteolytic enzymes are released." (PMID 39302568, 2024). "The coordinated action of TNF and IFN-γ is crucial for controlling TB infection; an insufficient response can lead to uncontrolled infection, while an excessive response can cause immunopathology." (PMID 38892443, 2024). "Instead, gene expression patterns returned to an almost pre-infection state by day3 p.i., while IL-8 and TNFα production was only observed on day7 and day14 p.i.." (PMID 38990812, 2024).
infection (continued). "IP-10 (CXCL10), TNF-α, and IL-6 were significantly upregulated in response to Delta infection, with concentrations of 3,236, 25.73, and 1,391 pg/mL, respectively." (PMID 38568894, 2024). "They showed lower concentrations of the MyD88-dependent cytokines TNF-α, IL-6 and G-CSF – all involved in the early stages of infection – thus suggesting the inability of RR in mounting an immediate inflammatory response." (PMID 39723217, 2024). "Infection with S. aureus induced TNF-α release by 42.5% and 1–3 decreased it by 43.9%, 44.9%, and 56.3%, respectively." (PMID 39458986, 2024). "IL-6 and TNF-α are cytokines that are promptly and transiently produced in response to infections and tissue injuries." (PMID 38611807, 2024). "Upregulated pathways were largely related to inflammation or infection, including coronavirus disease, nuclear factor kappa B (NF-kB) signaling pathway, TNF signaling pathway, cytokine-cytokine receptor interaction, and toll-like receptor signaling pathway." (PMID 38378873, 2024). "Murine fibroblasts and endothelial cells were reported to undergo apoptosis upon mCMV-ΔM36 infection only after conditioning by tumor necrosis factor α (TNFα)." (PMID 39146364, 2024). "Local production of cytokines, such as IL1β, IL6 and TNFα help amplify this proinflammatory response, while potent chemokines guide the neutrophils to the infection." (PMID 39509414, 2024). "Upon invasion of the body by MTB, TNF-α plays a crucial role in the innate immune response through its recruitment and activation of monocytes at the site of infection, thus enhancing their bactericidal activity." (PMID 38835752, 2024). "If the infection is found to be active, it is important to use antiviral treatment, possibly a month prior to the start of the anti-TNF and avoiding the use of RTX." (PMID 38979406, 2024). "Here, we found that PRRSV significantly induced the transcripts and proteins of interferon-α (IFN-α), IFN-β, IFN-γ, IFN-λ1, and tumor necrosis factor-α (TNF-α) in vitro primary porcine alveolar macrophages (PAMs) in the early stage of infection." (PMID 38962699, 2024). "Post-infection, excessive production of inflammatory mediators such as IL-1β, IL-6, IL-8, TNF-α, MCP-1, and IP-10, as well as the presence of endothelial inflammation markers (IL-6, TNF-α, ICAM-1) in lung tissues, have also been reported." (PMID 38600563, 2024). "In the current study, we treated BC 5,637 cells with LPS to mimic the inflammatory microenvironment caused by infection and found that LPS notably increased the levels of NLRP3 and inflammatory cytokines, including IL-1β, IL-18, and TNF-α." (PMID 39144184, 2024). "In the first phase, tissue damage or infection leads to the release of inflammatory mediators (e.g., histamine, prostaglandins, leukotrienes, tumor necrosis factor (TNF), interleukin-1 (IL-1), and interleukin-6 (IL-6))." (PMID 39334802, 2024). "Inflammatory cytokine assays demonstrate that compared to the mock group, IL-1β, IL-6, IL-8, and TNF-α were significantly upregulated in the lungs, spleen, intestines, and brain post-infection." (PMID 39170631, 2024). "Previous research has connected elevated levels of pro-inflammatory cytokines, particularly TNF-α, to more severe tissue damage at infection sites, resulting in severe ulcers and mucosal damage." (PMID 39199338, 2024). "Transient higher levels of IL-17A/F and TNF-α were observed at 30 min post infection in the ΔlytS mutant group, but at 24 and 32 hours post infection, levels of both cytokines were found to be significantly lower compared to the WT-infected animals." (PMID 39400158, 2024). "Inflammatory cytokines (such as IL-1β and TNF-α) in the PAMs infected with Del4L showed a significant increase compared with ASFV-WT infection at 12 and 20 hpi." (PMID 38501350, 2024). "The results showed that the expression levels of iNOS and TNFα were decreased in KCs at 2 months post-infection, while Arg1 was obviously increased." (PMID 38553755, 2024).
infection (continued). "Treatment with a ROS scavenger (N-acetyl cysteine, NAC) before infection with S. uberis reduced antioxidative responses and the inflammatory response, including the cytokines IL-6 and TNF-α, and the formation of the Atg5-LC3II/LC3I autophagosome." (PMID 38397769, 2024). "Frequencies of SARS-CoV-2-specific TNF-alpha+/IFN-gamma+ CD4+ T-cells declined over 12 months after infection (p < 0.01)." (PMID 38940003, 2024). "In the present study, haemonchosis elevated IL-3, IL-6, IL-10, and TNF-α gene expressions in abomasum tissue mRNA, which was attributed to the activation of the inflammatory cascade triggered by infection." (PMID 38963478, 2024). "Here, we corroborated this finding, showing that the anti-TNF neutralizing antibody Infliximab (Remicade) completely abrogated the rIFNγ-promoted infection of the human astrocyte U-87 MG cells by T. cruzi." (PMID 38776344, 2024). "Post-infection, cell supernatants were collected for ELISA assays, showing significantly elevated expression of TNF-α, IL-8, and IFN-γ compared to controls (p < 0.05)." (PMID 39600797, 2024). "Salmonella-specific Th1 cells produce pro-inflammatory cytokines (e.g., IFN-γ, TNF- α) during infection that activate phagocytes and promote clearance of bacteria from infected tissue." (PMID 38911854, 2024). "In comparison with the control group, the expression of Beclin‐1 and LC3 in the infection control group were slightly lower (p > .05), while the levels of PCT, TNF‐α, and IL‐6 in the infection stage group were significantly higher (p < .05)." (PMID 38577990, 2024). "In the PREVENT-COVID study cohort, comprising a majority of IBD patients on anti-TNF therapy, hospitalizations were rare even in those who experienced vaccine breakthrough infections." (PMID 39591183, 2024). "The primary infection primed monocytes and mDCs for an increased IL-6 and TNF-α production after restimulation with E. coli or TLR ligands ex vivo." (PMID 38474721, 2024). "A detailed temporal analysis of the pro-inflammatory cytokines secreted by human PBMCs showed an increased concentration of IL-1β, IL-6 and TNFα starting at 4 h post-infection, with IFNγ amounts rising at 8 h post-infection." (PMID 38793740, 2024). "Activated neutrophils release pro-inflammatory cytokines, such as TNF-α, IL-1β, and IL-6, exacerbating inflammation instead of providing protection as observed in infection and tissue injury scenarios." (PMID 38794163, 2024). "In fact, it was noticed that lower NO and TNF-α production levels were observed for all infections with Thor10/Thor22 combinations." (PMID 38985089, 2024). "G-MDSCs in the galea and bone flap and PMNs in the galea were also modestly reduced in TNF KO mice at day 7 post-infection." (PMID 39044282, 2024). "While neutrophils are essential for combating infection, they also contribute to tissue damage and organ dysfunction through the release of reactive oxygen species and pro-inflammatory cytokines such as tumor necrosis factor-alpha and IL-6." (PMID 39553003, 2024). "Generally, TNF-α levels peak in the early phases of infection and decrease significantly in the second week, except in patients with SDD." (PMID 39583156, 2024). "We found that levels of IL-6 at 24 hours after infection was significantly lower in the lungs of mice treated with CETPi compared with control, whereas levels of IL-1β and TNF-α were unchanged." (PMID 38646937, 2024). "Within 3 h of infection, compared to uninfected, WT-infected BMDMs showed 5-fold increased secretion of TNF-a, IL-1β and ~10-fold increase in MIP-1a and IP-10." (PMID 39063103, 2024). "We found Trim26–/–mice had higher levels of proinflammatory cytokine expression than Trim26+/+ mice, including IL-6, IL-1β, and TNF-α at day 5 post-infection." (PMID 38166150, 2024). "On the other hand, anti-TNF-α Ab treatment completely protected LysM Cre+Ifnarflox/flox mice from intraperitoneal lethal infection with DV3P12/08P4Bm." (PMID 38550855, 2024).
infection (continued). "Both beneficial and harmful effects have been described for TNF-α in the context of pneumococcal challenge, which depends on the time of infection and the compartment studied." (PMID 38675794, 2024). "At 4 h post-infection, all stimuli induced significantly higher gene expression levels of IL-8, TNF-α, MCP-1, and IL-1β." (PMID 39035711, 2024). "We also evaluated the changes in the concentration of cytokines produced by T cells at this time point post-infection: IL-4, TNF-α, and IFN-γ in BAL and serum." (PMID 38675794, 2024). "In contrast, administering a TNF-α agonist directly into the trachea of immunocompromised animals before infection significantly reduced the severity of the infection." (PMID 38667922, 2024). "We measured TNF-α, IL-1β, and IL-6 to confirm the immune system’s activation and the level of infection within the body." (PMID 39066795, 2024). "At 24 h post infection in 31 human lung explant tissue samples, key cytokines such as interleukin (IL)-6, IL-10, tumor necrosis factor-alpha (TNF-α), and interferon-gamma (IFN-γ) were upregulated." (PMID 39456722, 2024). "In particular, tumour necrosis factor α (TNF-α) is a typical cytokine produced by M1 macrophages and contributes to cell function in inflammation and infections." (PMID 38247825, 2024). "This study has shown that exposing macrophages to a lower concentration of GCA (250 nM) significantly increased the number of intracellular LF82 and stimulated the increased secretion of TNF-α after 72 h of infection." (PMID 39392674, 2024). "The mRNA expression of both IL-6 and TNF-α was found to be suppressed in the lungs of vaccinated hamsters as compared to unvaccinated infection control." (PMID 39911577, 2024). "Following a six-hour post-infection period, the IL-6 and TNF-α levels in mouse serum were quantified." (PMID 38912723, 2024). "Second, IL-10-induced JMJD2A and CHD1 can encourage genes desired in the regeneration of tissues after infection and prevent neutrophils from LPS-activation or TNF-preactivation." (PMID 38745328, 2024). "At the site of infection, macrophages release cytokines, such as interleukin (IL), tumor necrosis factor (TNF), which contribute to the body's inflammatory response." (PMID 38730482, 2024). "During infection, the hepatic synthesis of hepcidine is stimulated by several inflammatory cytokines, such as IL-6, IL-1, and TNFα." (PMID 38787184, 2024). "In various mouse strains, studies carry out with P. yoelii showed that IFN-γ and TNF produced 24 h after infection by γδ T lymphocytes and natural killer cells are indispensable for macrophage activation and early control of parasitaemia." (PMID 38962528, 2024). "Infection with N. gonorrhoeae produced a significant early6h response of IL-1β, TNF-α, and MIP-1β (CCL4)." (PMID 38704381, 2024). "We observed significant increases in TNF-α, IL-1β, and IL-8 expressions and a clear synergistic increase in IL-6 expression with the P. gingivalis and F. nucleatum co-culture infection." (PMID 38612423, 2024). "After infection of BMDMs and treatment during 24 h, we observed a significant decrease in the stimulation of TNF-α and IL-6 when the yeast cells were treated with TRB and 20 and 40 μg/mL of ML, when compared with untreated cells (1:10)." (PMID 39194287, 2024). "HuN2021 infection was accompanied by the upregulation of proinflammatory cytokines, such as IL-6, IL-1β, IL-8, TNF-α, and CCL8, as well as the immunomodulatory cytokines IL-10 and IFN-γ, at the mRNA and protein levels." (PMID 39506759, 2024). "And the levels of IL-6 and TNF-α were significantly higher in serum and lungs of Mettl3 cKO mice than those of Mettl3 WT mice upon infection with P. multocida, S. aureus, and M. pneumoniae." (PMID 38182816, 2024). "In DLD-1 cells, the expression of IL-1β and IL-8 were upregulated while TNF-α and IL-6 expression were downregulated after LV infection." (PMID 39427065, 2024).